SIRT1 (sirtuin 1)
Diseases named in the same sentence as SIRT1 in open-access papers (continued):
Sharing a sentence is not in itself a finding about the gene and the disease.
morbid obesity (1 paper, 2018). An excess of body weight, normally defined as an individual with a body mass index greater than 35 or a body weight greater than one hundred percent of ideal body weight. "In subjects with morbid obesity, decreased AT SIRT1 was observed in the insulin resistant vs. insulin sensitive group." (PMID 29417372, 2018).
motor neuron degeneration (1 paper, 2023). "In an in vitro model of ALS, resveratrol protects mutant-SOD-1-mediated toxicity by upregulating the expression of sirtuin-1 (SIRT-1) and motor neuron degeneration." (PMID 37627261, 2023).
MTHFR deficiency (1 paper, 2022).
mucinous ovarian cancer (1 paper, 2022). An invasive malignant neoplasm that arises from the ovary and is characterized by the presence of malignant epithelial cells that contain intracytoplasmic mucin and may resemble the epithelial cells of the endocervix or gastrointestinal tract. "Exposure to RSV was correlated with decreased Sirt1 expression in mucinous ovarian cancer cell-lines (A2780)." (PMID 34870752, 2022).
muscle disorders (1 paper, 2015). "Taken together, SIRT1-mediated deacetylation of Foxo1 may represent an important therapeutic mechanism of resveratrol in muscle disorders; although whether these findings would be extrapolated in compression-induced injury in the skeletal muscle warrant further research." (PMID 26557094, 2015).
myopia (1 paper, 2025).
nasopharyngitis (1 paper, 2025). An inflammatory process that affects the nasopharynx. "Additionally, pharmacological SIRT1 activators like SRT2104 have demonstrated side effects in clinical trials, including headaches, gastrointestinal disturbances, dizziness, and nasopharyngitis, often mild but highlighting tolerability concerns." (PMID 41281762, 2025).
nephrogenic diabetes insipidus (1 paper, 2022). Nephrogenic diabetes insipidus (NDI) is characterized by polyuria with polydipsia, recurrent bouts of fever, constipation, and acute hypernatremic dehydration after birth that may cause neurological sequelae. "The importance of SIRT1 in renal tissue was emphasized in SIRT1-null mice that developed nephrogenic diabetes insipidus, characterized by the production of large amounts of dilute urine due to the inability of the kidney to concentrate it." (PMID 35277012, 2022).
neuroendocrine prostate tumors (1 paper, 2018). "Importantly, amplification of SIRT1 was evident in neuroendocrine prostate tumors from TCGA database, providing validation of our expression analysis." (PMID 29416748, 2018).
obliterative bronchiolitis (1 paper, 2021). "Our study showed that APN suppressed proinflammatory factors (TNF-α and IL-6) through SIRT1- PINK1 signaling-mediated mitophagy, leading to inhibition of lung IR injury, which might mitigate the subsequent occurrence of acute graft rejection and obliterative bronchiolitis." (PMID 34602075, 2021).
ocular melanoma (1 paper, 2022). A melanoma that arises from the structures of the eye or ocular adnexa. "Furthermore, to unveil the relationship between SIRT1 and AMPK in autophagy regulation, we overexpressed SIRT1 in AMPK‐deficient ocular melanoma cells." (PMID 35075807, 2022). "Moreover, we determined that SIRT1 was significantly upregulated along with enhanced AMPK phosphorylation in a dose‐ and time‐dependent manner after stimulation with metformin in ocular melanoma cells." (PMID 35075807, 2022).
oculopharyngeal muscular dystrophy (1 paper, 2020). Oculopharyngeal muscular dystrophy (OPMD) is an adult-onset progressive myopathy characterized by progressive eyelid ptosis, dysphagia, dysarthria and proximal limb weakness. "In previous studies, overexpression of SIRT1 has been shown to ameliorate DMD pathophysiology in mdx mice, while salermide inhibition of SIRT1 has been shown to protect muscle cells against oculopharyngeal muscular dystrophy in Caenorhabditis elegans." (PMID 33059738, 2020).
onchocerciasis (1 paper, 2018). Onchocerciasis is a form of filariasis, caused by the parasitic worm Onchocerca volvulus, transmitted by the black fly. "Suramin, originally used for the treatment of trypanosomiasis and onchocerciasis, was described as a potent in vitro SIRTi (SIRT1, 2, and 5)." (PMID 29401749, 2018).
orthostatic hypotension (1 paper, 2025). Sudden fall of the blood pressure of at least 20/10 mm Hg when a person stands up. "SIRT1 expression levels resulted also correlated positively with the expiration/inspiration ratio (p = 0.016; r = 0.362) and with deep breathing (p = 0.005; r = 0.419), while VDR expression levels correlated negatively with the orthostatic hypotension (p = 0.049; r = − 0.279)." (PMID 39976627, 2025).
osteomyelitis (1 paper, 2026). An acute or chronic inflammation of the bone and its structures due to infection with pyogenic bacteria. "Serum SIRT1, SIRT3, apelin, and ELA levels were significantly lower in the DFI group and showed inverse correlations with HbA1c, PEDIS stage, disease duration, osteomyelitis, and inflammatory markers." (PMID 42195360, 2026).
osteophytes (1 paper, 2024). "Moreover, we did establish a significant association of NT/CT SIRT1 with the baseline appearance of osteophytes, and collagen type-II turnover." (PMID 38790038, 2024).
ovarian diseases (1 paper, 2024). "Increasing the levels of SIRT1 may represent an important way of treating ovarian diseases with drugs." (PMID 39232832, 2024).
ovarian serous cystadenocarcinoma (1 paper, 2020). A malignant serous cystic epithelial neoplasm arising from the ovary. "Only EGFR was significantly correlated with poor outcome (HR = 1.51, 95% CI 1.15–2, P = 0.0033) in ovarian serous cystadenocarcinoma, whereas SIRT1 predicted a good outcome (HR = 0.75, 95% CI 0.57–1, P = 0.047)." (PMID 32536817, 2020). "Pearson correlation analysis showed that EGFR (R = 0.16, P = 0.00072), PTEN (R = 0.098, P = 0.043), SIRT1 (R = 0.094, P = 0.013), RELA (R = 0.18, P = 0.00013) and CREB1 (R = 0.16, P = 0.00094) were significantly correlated with LDHAP5 expression in ovarian serous cystadenocarcinoma." (PMID 32536817, 2020).
Pancytopenia (1 paper, 2022). An abnormal reduction in numbers of all blood cell types (red blood cells, white blood cells, and platelets). "al. showed that by inducing resveratrol (RSV), a potent activator of SIRT1, in irradiated mice that presented medullary deficiency (pancytopenia)." (PMID 36230534, 2022).
Pca (1 paper, 2018). "Pathway and network analyses of SIRT1 were also generated based on neuroendocrine Pca cancer from TCGA database, and we found that SIRT1 could promote Pca progression via multiple pathways, including the HIF-1, SMAD4, and Akt pathways." (PMID 29416748, 2018). "We further examined the interaction between endogenous SIRT1 and Akt in Pca cells." (PMID 29416748, 2018). "in vitro experiments showed that SIRT1 was increased in Pca cells with ADT and that enhanced SIRT1 expression increased the levels of NED biomarkers." (PMID 29416748, 2018). "The results showed that SIRT1 transfection increased the phospho-Akt (p-Akt) level but did not affect other pathways, such as ERK and STAT, in both androgen-sensitive Pca cells (LNCaP) and androgen-independent Pca cells (PC3)." (PMID 29416748, 2018).
pelvic inflammatory disease (1 paper, 2022). Pelvic inflammatory disease (PID) is an acute or chronic inflammation in the pelvic cavity. "In the present study, we found that SSD exerted a protective effect on pelvic inflammatory disease through activation of the SIRT1 signaling and elimination of the NLRP3 inflammasome." (PMID 36106027, 2022). "Specifically, SIRT1 inhibitor EX-527 cotreatment significantly reversed the improvement effect of SSD on pelvic inflammatory disease in rats." (PMID 36106027, 2022).
periapical granuloma (1 paper, 2022). Chronic nonsuppurative inflammation of periapical tissue resulting from irritation following pulp disease or endodontic treatment. "The results showed that SIRT1 might affect angiogenesis in periapical granulomas, and the mechanism was based on the activation of endothelial cell proliferation, along with VE-cadherin and VEGF expression." (PMID 35630070, 2022).
peripheral nerve lesion (1 paper, 2018). "Together these results suggest that overexpression and subsequent enhanced activation of SIRT1 is neuroprotective in severe peripheral nerve lesions." (PMID 29382857, 2018).
peripheral sensory neuropathy (1 paper, 2024). "Further, CAPE has been shown to play a neuroprotective role by activation of SIRT1 expression in peripheral sensory neuropathy." (PMID 38528569, 2024).
peritonitis (1 paper, 2025). Inflammation of the peritoneum (tissue that lines the abdominal wall and covers most of the organs in the abdomen). "Similarly, previous studies have shown that Sirt1 upregulation via antisense RNA diminished lung edema, epithelial cell apoptosis, neutrophil infiltration, and inflammatory responses in a mouse model of peritonitis." (PMID 41096578, 2025).
plaque psoriasis (1 paper, 2020). "Next, we compared the expression of HDAC1, SIRT1, p63, and PCNA in guttate and plaque psoriasis." (PMID 32825671, 2020).
pneumoconiosis (1 paper, 2017). An occupational lung disorder caused by inhalation of dust particles. "Here, we also determined the expression of SIRT1 in lung specimens of pneumoconiosis patients, as well as primary alveolar macrophages and lung fibroblasts isolated from silica-exposed rats." (PMID 28698801, 2017).
Pompe disease (1 paper, 2018). "Thus, the role of SIRT1 in Pompe disease also deserves to be further explored." (PMID 30382921, 2018).
premature aging syndrome (1 paper, 2021). Changes in the organism associated with senescence, occurring at an accelerated rate. "This systematic review addresses the issue of sirtuin 1 relevance in skin aging in the context of intrinsic factors related to genetic premature aging syndromes as well as extrinsic modifiable ones with the assessment of its future application." (PMID 33917352, 2021).
renovascular hypertension (1 paper, 2021). High blood pressure secondary to renal artery stenosis. "Overall, the results of this study showed that the development of renovascular hypertension was associated with a SIRT1 reduction in the heart and ischemic kidney." (PMID 34730891, 2021). "Development of renovascular hypertension was associated with a reduction of SIRT1 expression in the heart and ischemic kidney." (PMID 34730891, 2021). "SIRT1 expression in the heart decreased in the acute phase and increased in the chronic phase of renovascular hypertension." (PMID 34730891, 2021). "Four and sixteen weeks after the induction of renovascular hypertension by clipping the left renal artery, systemic blood pressure, serum angiotensin II level, and the expression of Klotho and SIRT1 proteins and oxidative stress indices in the heart and kidneys were assessed." (PMID 34730891, 2021). "A combination of SIRT1 agonists and angiotensin II antagonists may be considered for use in the treatment of renovascular hypertension." (PMID 34730891, 2021).
retinal detachment (1 paper, 2024). An eye emergency condition which may lead to blindness if left untreated. "In a retinal detachment model, NMN treatment has shown an increment in retinal NAD+ levels and upregulated SIRT1 and heme oxygenase-1 (HO-1)." (PMID 38397799, 2024).
rhabdoid tumor (1 paper, 2013). An aggressive malignant embryonal neoplasm usually occurring during childhood. "First, several HDACs (including HDAC 1, 2, 5, 6, 9 and SIRT1) are, like in many other tumor entities, overexpressed in rhabdoid tumors." (PMID 23764045, 2013).
rheumatic diseases (1 paper, 2015). "It suggests that SIRT1 exerts a protective role in PAH associated with rheumatic diseases and can be a potential treatment target." (PMID 26273643, 2015).
Right ventricular hypertrophy (1 paper, 2025). In this case the right ventricle is more muscular than normal, causing a characteristic boot-shaped (coeur-en-sabot) appearance as seen on anterior- posterior chest x-rays. "Conversely, lower SIRT1 concentrations observed in diabetic patients and those with right ventricular hypertrophy suggest a complex, and context-dependent regulation of this protein." (PMID 41009597, 2025). "In contrast, decreased SIRT1 concentrations in patients with right ventricular hypertrophy may be attributed to chronic volume overload, which is common in advanced cardiorenal syndromes." (PMID 41009597, 2025).
rosacea (1 paper, 2026). A chronic erythematous skin disorder that affects the face. "MPV independently predicted rosacea (OR = 7.24; AUC = 0.827), whereas SIRT1 inversely correlated with disease risk." (PMID 41594223, 2026).
Rotavirus infection (1 paper, 2024). Infection with any of the rotaviruses. "Probiotics and/or prebiotics might improve intestinal cell apoptosis induced by rotavirus infection through elevating antioxidant capacity and regulating some related signaling pathways (including MAPK/ERK/JNK, SIRT1/FoxO1/Rab7)." (PMID 38698473, 2024). "And probiotics and/or prebiotics might decrease cell apoptosis, and increase cell migration during rotavirus infection, which was due that probiotics and/or prebiotics elevated antioxidant capacity, and regulated some related signaling pathways (including MAPK/ERK/JNK, SIRT1/FoxO1/Rab7)." (PMID 38698473, 2024).
sarcoidosis (1 paper, 2022). Sarcoidosis is a multisystemic disorder of unknown cause characterized by the formation of immune granulomas in involved organs. "SIRT1 is an essential mediator of energy metabolism and tissue survival, and INF-γ is necessary to develop and maintain the sarcoidosis status." (PMID 36405616, 2022).
schwannoma (1 paper, 2013). A benign, usually encapsulated slow growing tumor composed of Schwann cells. "Hence, there may be value to SIRT2 and SIRT1 combinatorial inhibition in schwannoma treatment." (PMID 24259290, 2013).
scrapie (1 paper, 2024). A fatal disease of the nervous system in sheep and goats, characterized by pruritus, debility, and locomotor incoordination. "The level of SIRT1 was significantly decreased in scrapie-infected models, and SIRT1 displayed the ability to protect neurons against cell death induced by PrP106–126." (PMID 39273653, 2024).
serine deficiency (1 paper, 2018). "Furthermore, impairment of the antioxidant defense system caused by maternal serine deficiency was mediated by the Akt/AMPK/Sirt1 pathway." (PMID 30305866, 2018). "However, whether Akt and Sirt1 are affected by serine deficiency remains unknown." (PMID 30305866, 2018).
silicosis (1 paper, 2022). Silicosis is a respiratory disease caused by breathing in (inhaling) silica dust. "Further investigations of the specific mechanisms by which Tet regulates the cytoskeleton and Sirt-1 are necessary to definitively understand its targets in silicosis." (PMID 34417574, 2022).
skin papilloma (1 paper, 2014). A benign papillary neoplastic growth on the skin composed of epithelial cells and a fibrous stalk. "We previously showed that locally applied resveratrol protects mice from the development of skin papillomas and that this protection is largely dependent on SIRT1." (PMID 25380034, 2014).
Sleep apnea (1 paper, 2015). An intermittent cessation of airflow at the mouth and nose during sleep is known as sleep apnea. "The increased locomotor activity, which is not a feature of CSD in sleep apnea, may increase neuroprotectants in the brain including SirT1 and BDNF." (PMID 26074865, 2015).
soft-tissue tumor (1 paper, 2013). "Recently, substantial expression of SIRT1 in soft-tissue neoplasms with myoid differentiation has been reported." (PMID 24019980, 2013). "Recently, common expression of SIRT1 in soft-tissue tumors with myoid differentiation compared with other types of soft-tissue tumor has been reported." (PMID 24019980, 2013).
stricture (1 paper, 2022). "SIRT1 has a protective effect on intestinal epithelial cells and can regulate the expression of inflammatory signaling pathways and related proteins to participate in the occurrence of intestinal stricture secondary to NEC." (PMID 35958178, 2022). "Therefore, we put forward a hypothesis of low expression of SIRT1 protein and overexpression of TGF-β1 protein in NEC secondary intestinal stricture tissue, where SIRT1 and TGF-β1 expressions are negatively correlated." (PMID 35958178, 2022). "The low expression of SIRT1 may promote the occurrence of intestinal stricture secondary to NEC." (PMID 35958178, 2022). "The expression of SIRT1 protein, which inhibits inflammatory response, was low in NEC secondary intestinal stricture and was negatively correlated with CRP expression." (PMID 35958178, 2022).
synovitis (1 paper, 2022). Inflammation of a synovial membrane. "Using a posttraumatic OA model (PTOA), we find that cartilage-specific Sirt1 genetic nulls caused severe synovitis and mineralization of the lateral joint compartment, due to augmented Lef1 gene expression." (PMID 35594394, 2022).
Telangiectasia (1 paper, 2014). Telangiectasias refer to small dilated blood vessels located near the surface of the skin or mucous membranes, measuring between 0.5 and 1 millimeter in diameter. "This is due to the phosphorylation of DBC1 at Thr454 by the ATM (ataxia telangiectasia-mutated) and ATR (ataxia telangiectasia and Rad3-related) kinases, which create a second binding site for SIRT1." (PMID 24567900, 2014).
temporal lobe epilepsy (1 paper, 2021). A localization-related (focal) form of epilepsy characterized by recurrent seizures that arise from foci within the temporal lobe, most commonly from its mesial aspect. "Moreover, inhibition of miR-181a-5p could exert a seizure-suppressing effect via SIRT1 upregulation, suggesting a potential role for the miR-181a-5p/SIRT1 pathway in the development of temporal lobe epilepsy." (PMID 33776649, 2021).
Thrombocytopenia (1 paper, 2024). A reduction in the number of circulating thrombocytes.
thrombotic disease (1 paper, 2019). The formation of a blood clot in the lumen of a vessel or heart chamber; causes include coagulation disorders and vascular endothelial injury. "A study found that in HepG2 cells, miR-23b-3p inhibits the synthesis of ApoA protein, which is a risk factor for thrombotic diseases, whereas another study reported that SIRT1, an enzyme that prevents lipid accumulation, was repressed by hsa-miR-23b-3p in hepatocytes." (PMID 31695969, 2019).
toxicity (1 paper, 2023). The degree to which an agent can damage an organism. "Our findings present the first evidence of the involvement of Sirt1 and HO-1 in the protective and antioxidant effects of CAS against APAP-induced liver toxicity in mice." (PMID 36839166, 2023).
urticaria (1 paper, 2024). A vascular reaction of the skin characterized by erythema and wheal formation due to localized increase of vascular permeability. "Whether SIRT1 is also involved in other cellular processes in the pathogenesis of urticaria is unknown." (PMID 39081309, 2024). "Since SIRT1 is a key regulatory factor in the regulation of glucose metabolism and insulin secretion, researchers have observed that SIRT1 can participate in the disorder of glucose metabolism in the skin tissue of urticaria mice, and up-regulation of SIRT1 can increase insulin secretion." (PMID 39081309, 2024).